INS (insulin)
Diseases named in the same sentence as INS in open-access papers (continued):
Sharing a sentence is not in itself a finding about the gene and the disease.
diabetes (continued). "The fact that diabetes status was a significant predictor of BMD in women independently of BMI may be partly explained by the anabolic effect that insulin has on bone tissue." (PMID 37268885, 2023). "Ultimately, bridging the gap between theoretical insights and practical applications could significantly impact the uptake of wearable insulin biosensors, potentially improving diabetes management and overall healthcare outcomes for affected individuals." (PMID 38239544, 2023). "DHEA may alleviate diabetes by increasing pancreatic insulin output as well as insulin sensitivity in the liver, fat, and muscle." (PMID 38075062, 2023). "Such measurements might help to characterize the parameters for each individual, similar in spirit to the use of glucose and insulin blood tests together with minimal models to evaluate insulin resistance and beta cell function in diabetes." (PMID 36818281, 2023). "In a hyperglycemic environment, reactive oxygen species (ROS) activate NLRP3 inflammatory vesicles in pancreatic β-cells, promoting IL-1β secretion leading to insulin secretion dysfunction, promoting obesity and insulin resistance, and ultimately inducing type 2 diabetes mellitus raw." (PMID 37443131, 2023). "Interestingly, individuals with T1DM face many problems seen in those with T2DM, with elevated body weight resulting in deteriorated insulin sensitivity, and as a consequence, are considered to have “double diabetes”." (PMID 37630716, 2023). "GWAS study showed prohormone convertase 1/3 (PC1/3) variants were associated with fasting proinsulin levels, and defective PC1/3 ER export could potentially contribute to impaired insulin biogenesis in diabetes." (PMID 37152949, 2023). "Rapamycin, an autophagy activator inhibiting mTORC1, can also worsen the diagnosis by leading to an increase in insulin resistance and reducing β-cell mass and function, adding reasons for caution while considering autophagy activation as a therapeutic goal in diabetes." (PMID 37759604, 2023). "This may be due to the hepatic insulin resistance or less portal levels of insulin in patients with early-onset diabetes." (PMID 37181070, 2023). "However, when there is an increased need for insulin, and the cells fail to respond to this demand, diabetes occurs." (PMID 37629550, 2023). "Multiple lines of evidence suggest that dietary probiotics able to restore normal gut microbiome composition can help to prevent and mitigate metabolic diseases, including diabetes, by improving the integrity of the intestinal barrier, reducing gut inflammation, and maintaining insulin sensitivity." (PMID 37181698, 2023). "Tirzepatide is a newly approved FDA drug that significantly reduces weight loss and improves insulin sensitivity in patients with and without diabetes." (PMID 37510690, 2023). "Investigating the impact of liver exosomes on insulin secretion represents a cutting-edge approach that may hold promise for future therapeutic interventions in diabetes." (PMID 38027137, 2023). "Baseline characteristics evaluated included age at enrollment, diabetes duration, sex, race/ethnicity, insulin modality (MDI versus CSII), metabolic status (HbA1c, C-peptide, hypoglycemia unawareness status), BMI, presence of nephropathy, education level, and household income." (PMID 37794113, 2023). "Understanding the mechanisms governing exosome release, cargo selection, and their subsequent impacts on insulin-producing pancreatic beta cells could pave the way for novel therapeutic opportunities for diabetes treatment." (PMID 38027137, 2023). "It is worth mentioning that some patients may require insulin to start with as a therapeutic agent, and those who already have diabetes prior to COVID-19 may need their insulin doses to be increased." (PMID 36839279, 2023).
diabetes (continued). "Qualitative studies with people from non-Western countries/ethnic minorities describe misconceptions regarding insulin and diabetes, injection fear, distrust of Western medicine, inconvenience, little family support, high-cost, religious beliefs, social stigma and body image as barriers." (PMID 37237318, 2023). "Buddleja officinalis (BOP) polysaccharides could improve diabetes by improving levels of blood glucose, blood lipids, and insulin and further improving CD34 expression." (PMID 37497112, 2023). "Lack of insulin leads to hyperglycemia (i.e. high blood glucose levels), which is associated with increased rates of diabetes complications, including neuropathy, retinopathy, and nephropathy." (PMID 36941696, 2023). "Increased exposure to diabetes technologies in people with type 2 diabetes (insulin pumps and glucose sensors) may mitigate some of these negatives if the glycemic benefits are perceived to be worthwhile." (PMID 36631592, 2023). "It was also associated with taking insulin in those with diabetes, but only when not controlling for HbA1c in the regression." (PMID 36891143, 2023). "In addition to direct damage, SARS-CoV-2 can also induce autoimmune reactions, resulting in β-cell dysfunction and reduced insulin release, and increased insulin resistance in peripheral tissues, leading to the onset or exacerbation of diabetes mellitus (DM)." (PMID 37286981, 2023). "Furthermore, we discovered that IVSd is significantly thickened in neonates born to moms who took insulin to control their diabetes during pregnancy, and that male infants had a greater LVIDd than female infants." (PMID 37553638, 2023). "Therefore, it is very important to strengthen the supply of basic insulin and drugs for diabetes in economically underdeveloped areas." (PMID 37400673, 2023). "Insufficient insulin secretion to meet metabolic demand results in diabetes." (PMID 37787501, 2023). "The resistance to insulin secondary to the excess of growth hormone is compensated by the increased secretion of insulin from the pancreatic β cells, and over time, with the decrease in the secretory capacity of the pancreas, prediabetes and diabetes can set in." (PMID 37628857, 2023). "In this review, we summarize current knowledge on the molecular mechanisms of vitamin D in insulin secretion, insulin sensitivity, and immunity, as well as the observational and interventional human studies investigating the use of vitamin D as a treatment for diabetes." (PMID 37111216, 2023). "Type 2 diabetes mellitus (T2DM) mostly occurs in adults when the body becomes resistant to insulin." (PMID 37529488, 2023). "It is reassuring that the effects of OPG and DMB on the β cell, hepatocytes, muscle, fat, and bone are beneficial in the context of diabetes, as they enhance β cell growth, function, and survival; improve hepatocyte, muscle, and adipose insulin sensitivity; and augment bone formation." (PMID 37910614, 2023). "Approximately 7.4 million Americans with diabetes used insulin." (PMID 36751859, 2023). "The contradictory finding that carriers of the RREB1 protective allele have lower insulin secretion levels but are protected from type 2 diabetes hints at potential additional functions of RREB1 in other diabetes-relevant tissues (e.g. insulin-responsive tissues)." (PMID 36633628, 2023). "Thus, the overall results in analysis of patients with diabetes mellitus strongly depend on the percentage of patients with diabetes on insulin." (PMID 36975883, 2023). "Surgical removal of small tumors, while preserving the insulin-producing islets in the tail of the pancreas, can improve insulin sensitivity and effectively eliminate diabetes, further supporting this hypothesis." (PMID 37697301, 2023). "Interventions on the microbiome could alter the course and natural history of diabetes in young patients, delaying insulin therapy and helping preserve pancreatic beta cells." (PMID 36979685, 2023).
diabetes (continued). "Insulin pump therapy, rtCGM, and the use of both treatment modalities significantly increase the mean diabetes-associated costs when compared to no technology users (mean € 2,418, median €1,506, IQR 808—2,702)." (PMID 37029362, 2023). "The third type of diabetes management is the insulin pumps that deliver insulin." (PMID 37512604, 2023). "Therefore, the mechanism after topical insulin administration is still unclear with respect to accelerated corneal epithelialization in people with diabetes." (PMID 38068983, 2023). "To date, patients with type 1 diabetes mellitus should be educated to begin physical activity early, as well as insulin therapy, as part of their treatment plan and to prevent complications that may be associated with a long duration of the disease." (PMID 37892734, 2023). "Diabetes mellitus is a metabolic disorder, characterized by hyperglycemia, affecting carbohydrate, fat, and protein metabolism, resulting from abnormal insulin secretion, insulin resistance, or both of these factors." (PMID 36672202, 2023). "MetS, obesity, and diabetes induce adverse effects on skeletal muscle function, including muscle fiber atrophy and contractile dysfunctions, altered metabolism, insulin resistance, oxidative stress, mitochondrial dysfunctions, and reduced regenerative potential." (PMID 37049607, 2023). "Reduce β-cell mass and decreased insulin secretion are key pathologic events for diabetes." (PMID 37903776, 2023). "Diabetes mellitus (DM) is considered a group of metabolic diseases characterized by hyperglycemia (high concentration of blood D-glucose), resulting from defects in insulin secretion, insulin action, or both." (PMID 36276938, 2022). "Nurses’ perception increased post-study: By using the basal insulin algorithm, the individual BG adjustment of the participants was performed more efficiently, errors and acute diabetes- related hospitalizations could be avoided." (PMID 36992745, 2022). "A-type PAC oligomers of C. tamala improved the insulin concentration in the blood and pancreas, whereas C. zeylanicum A-type PACs potentiated insulin action, and may be beneficial in the control of glucose intolerance and diabetes." (PMID 36500445, 2022). "Also, the study showed that some first contact with an insulin pump brought feelings of the onset of the disease and negative emotions that accompanied the patients at the time when they were diagnosed with diabetes." (PMID 36687959, 2022). "There were 2482 participants with diabetes using insulin included in the analyses (mean [SD] age, 59.8 [0.4] years); 51.3% were men, 7.0% were Mexican American individuals, 17.9% were non-Hispanic Black individuals, and 65.2% were non-Hispanic White individuals." (PMID 36538330, 2022). "In recent years, attention has been paid to the relationship between β-cell dedifferentiation and trans-differentiation in diabetes, in which the percentage of INS-positive cells in the islet structure is decreased and the corresponding percentage of GLU-positive cells is increased." (PMID 36467676, 2022). "In addition, regular physical activity also provides considerable benefits for cardiovascular health, muscle strength, and insulin sensitivity in type 1 diabetes mellitus patients." (PMID 35742478, 2022). "Diabetes is classified into two types, the first one being type I DM, which is an autoimmune disorder wherein the β cells are destroyed, affecting the secretion of insulin." (PMID 35956932, 2022). "The studies from MEDIM have previously demonstrated that Iraqi immigrants irrespective of diabetes related risk factors, are more insulin resistant compared to native Swedes, which can contribute to increased risk of atherosclerosis." (PMID 36309585, 2022). "However, it is critical for people with diabetes to use resources other than online crowdfunding to access and obtain insulin owing to low success rates." (PMID 35436214, 2022).
diabetes (continued). "All individuals have insulin-requiring diabetes by virtue of using an open-source AID." (PMID 35565875, 2022). "Accordingly, the American Diabetes Association (ADA) has recently recommended its use for the management of both patients with type 1 (T1DM) and type 2 (T2DM) diabetes mellitus treated with multiple daily insulin injections." (PMID 36030229, 2022). "Hereby, subjects with a predominant lack of insulin production and others with considerable insulin resistance are burdened with the greatest risk for diabetes complications." (PMID 36432409, 2022). "Moreover, early insulin response in the first 30 min following oral glucose ingestion is clearly reduced in subjects with type 2 diabetes mellitus." (PMID 35453469, 2022). "Glucose-responsive systems are well-known approaches for insulin delivery to treat diabetes." (PMID 35215689, 2022). "We aimed to investigate, using real-world data, whether switching to dulaglutide improves glycemic control in patients with type 2 diabetes mellitus (T2D) inadequately controlled with conventional insulin treatment." (PMID 35784534, 2022). "Data from our 4 studies suggest that insulin sensitivity and C-peptide physiology articulate a unified mechanistic model for early dyslipidemia across the lifespan in both children and adults with diabetes mellitus." (PMID 35432186, 2022). "An insufficient response to the demand for insulin results in diabetes." (PMID 35603790, 2022). "Potential oncogenic effects of recombinant analogs of human insulin used for treatment of diabetes may relate to their differing binding affinities with the insulin vs. IGF-1 receptors." (PMID 35158824, 2022). "Plasma NfL level is associated with diabetes status and plasma glucose levels but not plasma insulin levels or HOMA-IR in a cohort of middle-aged adults with PD and T2D." (PMID 35795150, 2022). "The people with T2DM using insulin had poor diabetes knowledge (92.3%)." (PMID 36527016, 2022). "Of the 617 patients with known diabetes, 301 were treated with metformin, 245 with insulin, 106 with dipeptidyl peptidase four inhibitors, 75 with SGLT2 inhibitors, 47 with glucagon-like peptide one receptor analogues and 38 with sulphonylureas (including repaglinide)." (PMID 36600650, 2022). "Apart from whole pancreas or islet transplantation, β cells may also be replaced by transplanting human pluripotent stem cell (hPSC)‐derived β cells into diabetes patients to achieve insulin independence." (PMID 35474596, 2022). "The side effects of diabetes medications, especially insulin, are unavoidable and may occur in patients who inject insulin." (PMID 35832786, 2022). "We believe that our results provide new information on the molecular mechanisms at the basis of insulin processing in pancreatic cells and could also offer insights into the diabetes mellitus drugs therapeutic field." (PMID 35330199, 2022). "Thus, which is the culprit for the worse outcome in patients with COVID-19 and diabetes, hyperglycemia or insulin?" (PMID 35723340, 2022). "Comorbidities can be treated strictly, including strict insulin control for diabetes." (PMID 35774696, 2022). "Diabetes mellitus consists of a cluster of metabolic diseases marked by elevated glucose levels, which may result from defects in insulin action, insulin secretion, or both." (PMID 35677892, 2022). "A recent analysis of 151,194 participants from three prospective U.S. cohorts has showed that individuals with insulin-treated diabetes had 43% higher OSA risk when compared to those without diabetes." (PMID 35268504, 2022). "However, some issues, including barriers and facilitators to diabetes management with insulin, need more attention because people with intellectual disabilities experience inequitable access to diabetes education and healthcare." (PMID 35983585, 2022).
diabetes (continued). "According to recent data stemming from the use of single-cell RNA sequencing, several both sex-specific and sex-independent differentially expressed genes (DEGs) related to insulin secretion and pathophysiology of diabetes have been identified in healthy and diabetic mice." (PMID 35330453, 2022). "Nerveless, peripheral administration of insulin is not a viable route due to the risk of systemic hypoglycemia or induction/increase in insulin resistance also in individuals who do not have diabetes." (PMID 35741464, 2022). "Diabetes, a global health concern, requires insulin therapy." (PMID 35546683, 2022). "Regardless, our study is the first to demonstrate the proapoptotic properties of insulin on cardiomyocytes in diabetes, and that may also account for the worsened clinical outcomes among insulin-utilizing diabetic patients." (PMID 35574440, 2022). "Furthermore, the participants expressed a need for more visual content that covered other important issues in diabetes such as how insulin therapy works, daily self-monitoring of blood glucose, HbA1c testing, and foot care." (PMID 35943787, 2022). "Diabetes medications are prescribed to perform a variety of essential metabolic functions such as controlling blood glucose levels, stimulating the production of insulin, and regulating the digestion of carbohydrates." (PMID 35619860, 2022). "Indeed, it was demonstrated that pancreatic α-cells and δ-cells become insulin expressers upon ablation of insulin-secreting β-cells, promoting diabetes recovery." (PMID 35185804, 2022). "However, the poor liposolubility, inactivation and high molecular weight of injected insulin reduce its bioavailability, leading to chronic complications in diabetes." (PMID 36012342, 2022). "In contrast, the use of insulin was associated with decreased survival compared with the non-diabetes group." (PMID 35337110, 2022). "In this cross-sectional study, it was reported an association with insulin sensitivity in a Caucasian population, without association with diabetes mellitus." (PMID 35126789, 2022). "Factors that can lead people with diabetes to produce IAs include the recipient’s immune response genes, age, the insulin purity, molecular structure, storage condition, formulation of insulin and the sites and methods of insulin delivery." (PMID 36440205, 2022). "Finally, the proteins in this group associated with metabolic regulation such as the insulin signaling pathway and cholesterol metabolism may enhance the metabolic pathway, leading to an improvement in insulin resistance and prohibit the progression of diabetes." (PMID 36364802, 2022). "The PubMed and Web of Science online databases were searched to identify relevant studies published in the English language using the terms “Prader–Willi syndrome” with “glucose”, “insulin”, “diabetes mellitus”, “fat”, “adipo*”, “ghrelin”, “oxytocin”, “irisin” or “autonomic nervous system”." (PMID 35525976, 2022). "This topic has recently attracted attention in the scientific world, and many studies in that field were conducted, not only in relation to PCOS, but also in respect to other conditions involving defective insulin signaling, such as obesity, diabetes mellitus, and gestational diabetes." (PMID 35206286, 2022). "Consequently, because of the progressive nature of the disease, patients with type 2 diabetes mellitus (T2DM) have been initiated with insulin-based therapy." (PMID 36149907, 2022). "As insulin is secreted by the pancreatic islet cells, pigs—with a pancreas similar in size, shape, and blood circulation to the human pancreas—have become an attractive diabetes model." (PMID 35343091, 2022). "Berberine is useful for the management of diabetes by acting as an insulin secretagogue." (PMID 36145160, 2022). "Therefore, reduction in body weight or visceral fat implied the improvement in insulin sensitivity, thereby preventing diabetes and cardiovascular disease." (PMID 35371260, 2022).